USP10 (ubiquitin specific peptidase 10)
Diseases named in the same sentence as USP10 in open-access papers (continued):
Sharing a sentence is not in itself a finding about the gene and the disease.
A further 9 diseases each share a sentence with USP10 in 1 paper.